CHAF1A (chromatin assembly factor 1 subunit A)
Description:
Acts as a component of the histone chaperone complex chromatin assembly factor 1 (CAF-1), which assembles histone octamers onto DNA during replication and repair. CAF-1 performs the first step of the nucleosome assembly process, bringing newly synthesized histones H3 and H4 to replicating DNA; histones H2A/H2B can bind to this chromatin precursor subsequent to DNA replication to complete the histone octamer. It may play a role in heterochromatin maintenance in proliferating cells by bringing newly synthesized cbx proteins to heterochromatic DNA replication foci.
Synonyms: CAF1P150; CAF1B; CAF-1; CAF1; P150; MGC71229
Tractability: PROTAC: UniProt records ubiquitination sites on it; ubiquitination databases record sites on it.
Gene: Protein-coding gene on chromosome 19 (4,402,617 to 4,445,018, forward strand). Ensembl gene ENSG00000167670.
Subcellular location: Nucleus
Subcellular location (Human Protein Atlas): Nucleoplasm; Cytosol
Gene Ontology:
Molecular function: chromo shadow domain binding; identical protein binding; protein binding; chromatin binding
Biological process: DNA replication-dependent chromatin assembly
Cellular component: CAF-1 complex; chromatin; nucleoplasm; protein-containing complex; nucleus
Genetic constraint (gnomAD): Loss-of-function variants: 4 observed, 83.78 expected, observed/expected ratio (o/e) 0.0477, 90% interval 0.023 to 0.11. The upper end of that interval is the gene's LOEUF score, 0.11, which puts it in group 1 of 6, group 1 being the genes least tolerant of losing a copy. Missense variants: 1,051 observed, 1,218.3 expected, observed/expected ratio (o/e) 0.86, 90% interval 0.82 to 0.91. Synonymous variants: 480 observed, 498.95 expected, observed/expected ratio (o/e) 0.96, 90% interval 0.89 to 1.04.
Homologues: Orthologues: chimpanzee CHAF1A (99% identical), macaque CHAF1A (94% identical), dog CHAF1A (80% identical), pig CHAF1A (78% identical), guinea pig CHAF1A (69% identical), rat Chaf1a (65% identical), mouse Chaf1a (65% identical), tropical clawed frog chaf1a (45% identical), zebrafish chaf1a (40% identical), Caenorhabditis elegans chaf-1 (16% identical).
Diseases named in the same sentence as CHAF1A in open-access papers:
CHAF1A is named in the same sentence as 40 diseases in open-access papers, as found by Europe PMC text mining. Sharing a sentence is not in itself a finding about the gene and the disease. The quoted sentences say what the papers report.
breast carcinoma (6 papers, 2021 to 2025). "CHAF1A has been identified as an oncogene in various tumors, such as colorectal cancer and breast cancer, where it is associated with cell proliferation, metastasis, apoptosis, and poor patient prognosis." (PMID 40797060, 2025). "Recently, CHAF1A has been associated with the development and progression of solid tumors, including breast cancer, prostate squamous cell carcinoma, hepatocellular carcinoma (HCC), glioma and neuroblastoma." (PMID 33616161, 2021). "Furthermore, we found that elevated expression of CHAF1A is positively associated with glycolysis in breast cancer." (PMID 36968583, 2023). "The major biological effects and signaling pathways demonstrated that CHAF1A played important roles in breast cancer progression." (PMID 36968583, 2023). "Both mRNA expression and protein expression of CHAF1A were significantly elevated in breast cancer samples compared with normal samples." (PMID 36968583, 2023). "As such, the data suggest that elevated expression of CHAF1A is a prognostic biomarker of poor patients’ outcome in breast cancer." (PMID 36968583, 2023). "The expression of CHAF1A is much higher in breast cancer tissues compared with benign ones as shown by the IHC images." (PMID 36968583, 2023). "Thereby, further functional study of CHAF1A would better validate its potential role as biomarker and target in breast cancer." (PMID 36968583, 2023). "Elevated expression of CHAF1A was positively correlated with breast cancer progression and poor patients’ outcome." (PMID 36968583, 2023). "Our study not only confirmed CHAF1A abnormally high expression in cancers especially in breast cancer, but also demonstrated a strong correlation between CHAF1A overexpression, breast cancer molecular subtype, prognosis and treatment response." (PMID 36968583, 2023). "Meanwhile, CHAF1A has also been found to play an important role in colon cancer, breast cancer and other tumors, which is related to cell proliferation, metastasis, apoptosis and poor prognosis of patients." (PMID 37575547, 2023). "In breast cancer, it was found that the expression of CHAF1A was negatively correlated with CD8+ T cell, but positively correlated with regulatory T cell (Treg) and MDSC (Myeloid-derived suppressor cell)." (PMID 36968583, 2023). "CHAF1A protein expression in breast cancer correlates with Ki-67 expression, poor histological grade, high mitotic index and decreased DFS." (PMID 34073937, 2021). "There are few studies focused on CHAF1A, although some have reported its reduction in squamous cell carcinoma and breast cancer, indicating potential and anti-cancer effects." (PMID 35087762, 2021). "A number of studies have shown that CHAF1A is also highly expressed in breast cancer, colon cancer, CC and other tumors, and can be used as a potential marker for judging the prognosis of tumor patients and a target for tumor treatment." (PMID 33616161, 2021). "Furthermore, the expression of CHAF1A was significantly higher in TNBC than either luminal or HER2 positive breast cancer." (PMID 36968583, 2023). "Moreover, elevated expression of CHAF1A is a promising prognostic predictor and potential biomarker of drug resistance in breast cancer." (PMID 36968583, 2023). "Here, we provide evidence to demonstrate that CHAF1A could be served as a promising biomarker for breast cancer diagnosis, prognosis, sensitivity of immunotherapy and target of therapeutics." (PMID 36968583, 2023).
breast carcinoma (continued). "Since the co-expression network analysis indicated that immune system might be involved, we looked deep into the tumor-infiltrating immune cells of breast cancer samples to investigate the correlation between CHAF1A and immune response in TIMER 2.0 database." (PMID 36968583, 2023). "As such, breast cancer patients with higher expression of CHAF1A might progress into treatment resistance to endocrine therapy and chemotherapy in shorter time." (PMID 36968583, 2023). "In addition, we demonstrated statistically significant correlation between elevated CHAF1A expression and poor breast cancer patients’ outcome." (PMID 36968583, 2023). "Functional validation of CHAF1A was applied in breast cancer." (PMID 36968583, 2023). "Thereby, we have shown the comprehensive profile of CHAF1A in breast cancer." (PMID 36968583, 2023). "Overexpression of CHAF1A was found in breast cancer tissues compared to benign tissues." (PMID 36968583, 2023). "It was shown that the breast cancer patients with elevated expression of CHAF1A showed significantly shorter recurrence free survival whether receiving endocrine therapy or chemotherapy." (PMID 36968583, 2023). "And CHAF1A targeting therapy combined with immune checkpoint inhibitors might achieve synergistic effect for breast cancer patients with increased expression of CHAF1A." (PMID 36968583, 2023). "Elevated expression of CHAF1A was confirmed in breast cancer tissues." (PMID 36968583, 2023). "Since elevated expression of CHAF1A may cause accumulation of MTA via regulating amino acid metabolism, it is possible that purine analogue might be potential treatment option in MTAP deletion breast cancer patient with higher expression of CHAF1A." (PMID 36968583, 2023). "Furthermore, among the subtypes of breast cancer, the expression of CHAF1A was significantly higher in triple negative breast cancer (TNBC) compared to either luminal or HER2 positive breast cancers in both mRNA level and protein level." (PMID 36968583, 2023). "As such, breast cancer patients with higher expression of CHAF1A might benefit from immune checkpoint inhibitors." (PMID 36968583, 2023). "The results suggest that the elevated expression of CHAF1A may serve as a poor prognostic biomarker in breast cancer." (PMID 36968583, 2023). "As such, CHAF1A may be a potential therapeutic target of breast cancer." (PMID 36968583, 2023). "As such, CHAF1A could be potential therapeutic target in breast cancer." (PMID 36968583, 2023). "Higher expression of CHAF1A induced fast resistance to endocrine therapy and chemotherapy, it may be a promising therapeutic target and a biomarker to predict the sensitivity of immunotherapy in breast cancer." (PMID 36968583, 2023). "It was interesting to find that the elevated expression of CHAF1A was negatively correlated with CD8+ cell, but positively correlated with Treg and MDSC in breast cancer." (PMID 36968583, 2023). "Interestingly, cancer metabolism was of the most outstanding generated by various analyses, which suggested that CHAF1A might be critical to breast cancer development and progression, thus might provide novel therapeutic target for the treatment of breast cancer." (PMID 36968583, 2023). "Moreover, cell proliferation was inhibited when CHAF1A was silencing in MDA-MB-231 cells, indicating that CHAF1A played important role in breast cancer cell growth." (PMID 36968583, 2023). "Furthermore, silencing of CHAF1A can significantly inhibit MDA-MB-231 cell proliferation, which suggests that CHAF1A can serve as potential therapeutic target of breast cancer." (PMID 36968583, 2023). "Since we found that CHAF1A could induce metabolic reprogramming in breast cancer, it was not surprising that patients with increased CHAF1A expression developed drug resistance in a relatively short period of time." (PMID 36968583, 2023).
breast carcinoma (continued). "Elevated expression of CHAF1A was significantly correlated with shorter overall survival (OS), shorter recurrence free survival (RFS), and shorter distant metastasis free survival (DMFS) of breast cancer patients obtained from Kaplan-Meier plotter (Győrffy, 2021) survival analysis." (PMID 36968583, 2023). "Moreover, there was no study about the functional roles and mechanisms of CHAF1A in breast cancer." (PMID 36968583, 2023).
neuroblastoma (6 papers, 2013 to 2025). Neuroblastoma (NB) is the most common solid, extracranial childhood tumor. "With this approach we identified four genes that are highly over expressed in high-risk neuroblastoma (CHAF1A, RRM2, MCM3, and MCM6) whose expression strongly correlates with poor outcomes." (PMID 24348903, 2013). "Thus, CHAF1A significantly restricts neural crest differentiation and the pathogenesis of high-risk neuroblastoma." (PMID 39996888, 2025). "This study identifies CHAF1A, a histone chaperone and epigenetic regulator, as crucial in maintaining the aggressive dedifferentiated state of neuroblastoma." (PMID 39996888, 2025). "In recent years, studies have suggested that the elevated expression of CHAF1A is closely correlated with the development of some types of cancer, such as neuroblastoma, lung cancer, ovarian cancer, and gastric cancer." (PMID 36968583, 2023). "Furthermore, the combined inhibition of the direct identified targets such as CCND1, CHAF1A, INCENP and BCL-XL could reveal new vulnerabilities of high-risk neuroblastoma." (PMID 30770954, 2019). "In addition, it was reported that abnormally elevated expression of CHAF1A could regulate the metabolic pathways of some amino acids, such as methionine, eventually inducing 5′-methylthioadenosine (MTA) accumulation in neuroblastoma." (PMID 36968583, 2023).
gastric cancer (5 papers, 2021 to 2023). A primary or metastatic malignant neoplasm involving the stomach. "CHAF1A expression is also associated with the survival of gastric cancer patients after radical gastrectomy and fluoropyrimidine-based (5-FU) adjuvant chemotherapy." (PMID 34073937, 2021). "CHAF1A is overexpressed in gastric cancer cell lines and tissue samples, and its high expression predicts poor prognosis." (PMID 37575547, 2023). "It was reported that CHAF1A could bind to the DNA promoter region of c-Myc to enhance the transcriptional expression of c-Myc in gastric cancer, which was consistent with the current finding that CHAF1A was positively correlated with Myc targets." (PMID 36968583, 2023). "This was consistent with the research finding that elevated expression of CHAF1A could promote thymidylate synthetase activity, leading to 5-FU resistance in gastric cancer." (PMID 36968583, 2023). "Similarly, using bioinformatics analysis, another concurrent study has shown that a G2/M checkpoint-related signature composed of five genes (MARCKS, CCNF, MAPK14, INCENP, and CHAF1A) was connected with the prognosis of gastric cancer (GC) patients." (PMID 35419294, 2022). "CHAF1A mRNA and protein are also overexpressed in gastric cancer." (PMID 34073937, 2021). "In addition, studies have demonstrated that CHAF1A may affect the efficacy of adjuvant chemotherapy in gastric cancer by regulating the expression of thymidylate synthase." (PMID 37575547, 2023). "The overexpression of CHAF1A is an independent prognostic factor for poor response to 5-FU chemotherapy (reduced OS and DFS) in non-cardia gastric cancer." (PMID 34073937, 2021).
hepatocellular carcinoma (5 papers, 2021 to 2024). A malignant tumor that arises from hepatocytes. "Intensive documents have implicated that CHAF1A is abnormally regulated or expressed in various malignancies, including neuroblastoma, prostate cancer, breast cancer, as well as hepatocellular carcinoma (HCC)." (PMID 35773729, 2022). "Similar to tumours of the gastrointestinal tract, CHAF1A protein is overexpressed in hepatocellular carcinoma (HCC) and represents an independent prognostic factor indicative of reduced OS and DFS." (PMID 34073937, 2021). "CHAF1A, CEP192, and AS3MT were reported to be associated with tumor progression involved with several tumors, such as hepatocellular carcinoma and lung cancer Further explorations are needed to investigate the biological mechanisms of these 6 shared genes on IS and obesity." (PMID 39734234, 2024).
colon cancer (3 papers, 2021 to 2023). "Functional experiments revealed that CHAF1A promotes proliferation and inhibits the apoptosis of colon cancer cells." (PMID 34073937, 2021). "CHAF1A mRNA and protein expression are upregulated in colon cancer." (PMID 34073937, 2021).
glioblastoma (3 papers, 2022 to 2023). The most malignant astrocytic tumor (WHO grade IV). "The inhibition of CHAF1A also blocked the AKT /FOXO3a /Bim signaling pathway for glioblastoma cell proliferation." (PMID 36672345, 2023). "The chromatin assembly factor 1 subunit A (CHAF1A) is highly expressed in glioblastoma cells, and the highly expressed CHAF1A is related to poor prognosis following glioblastoma treatment, which further promotes the proliferation of glioblastoma cells." (PMID 36672345, 2023). "The expression of CHAF1A was positively correlated with the tumor size and clinical stage of glioblastoma, and negatively correlated with the overall survival rate, which could be used as an independent biological marker to estimate the prognosis." (PMID 37575547, 2023). "It was suggested that CHAF1A could affect cell proliferation and apoptosis through AKT/FOXO3a/Bim pathway in glioblastoma." (PMID 37575547, 2023).
ovarian carcinoma (3 papers, 2023 to 2025). A malignant neoplasm originating from the surface ovarian epithelium. "Previous studies of our group have shown that CHAF1A acts as a growth promoting agent in epithelial ovarian cancer, and its high expression is associated with clinical stage and lymph node metastasis, which can promote cancer cells proliferation and inhibit cancer cells apoptosis." (PMID 37575547, 2023). "Ovarian cancer—in vitro studies using ovarian cancer cell lines with knockdown or overexpression of CHAF1A (chromatin assembly factor 1 unit A) that induces cell proliferation and growth, showed an inhibitory effect of Peficitinib." (PMID 41463071, 2025). "Secondly, it is necessary to validate the expression of CHAF1A in a larger cohort, and analyze the relationship between CHAF1A and prognosis of ovarian cancer in future study." (PMID 37575547, 2023). "After inhibiting JAK2/STAT3 pathway, the promoting effect of CHAF1A on epithelial ovarian cancer cell proliferation disappeared, meanwhile the inhibitory effect of CHAF1A on apoptosis enhanced." (PMID 37575547, 2023). "The molecular mechanism of chromatin assembly factor 1 unit A (CHAF1A) promoting the proliferation and growth of epithelial ovarian cancer (EOC) cells hasn’t been reported at present." (PMID 37575547, 2023). "In conclusion, CHAF1A promotes the proliferation and growth of epithelial ovarian cancer cells by affecting the phosphorylation of JAK2/STAT3 signaling pathway." (PMID 37575547, 2023). "We found that compared with normal ovarian epithelial tissues, CHAF1A was highly expressed in epithelial ovarian cancer tissues and correlated with patient stage upgrading and lymph node metastasis by analyzing TCGA database and combining with our published articles." (PMID 37575547, 2023). "We further investigated the downstream pathways affected by CHAF1A in epithelial ovarian cancer." (PMID 37575547, 2023). "Bioinformatics analysis suggested that CHAF1A was up-regulated in epithelial ovarian cancer." (PMID 37575547, 2023). "•Inhibition of JAK2/STAT3 signaling pathway could reduce the effect of CHAF1A overexpression on the proliferation and growth of epithelial ovarian cancer cells." (PMID 37575547, 2023). "In unpaired samples, CHAF1A expression was significantly up-regulated in ovarian cancer." (PMID 37575547, 2023). "Further cytofunctional experiments showed that CHAF1A could promote the proliferation and inhibit cell apoptosis of epithelial ovarian cancer cells." (PMID 37575547, 2023). "Similarly, we also found high expression of CHAF1A in epithelial ovarian cancer cell lines." (PMID 37575547, 2023). "CHAF1A promotes the proliferation and growth of epithelial ovarian cancer cells and inhibits the apoptosis of cancer cells by activating JAK2/STAT3 signaling pathway, which is expected to be a new target for the treatment of epithelial ovarian cancer." (PMID 37575547, 2023). "However, there was no literature report on the relationship between CHAF1A and ovarian cancer before our study." (PMID 37575547, 2023).
bladder cancer (2 papers, 2023 to 2025). "In addition, in bladder cancer cell J82 with down-regulated expression of CHAF1A, some down-regulated expression of several genes related to cell growth and proliferation were found, including STAT2, STAT6, AKT2, IRS1 and SOX4." (PMID 37575547, 2023). "In the study of bladder cancer, human gene expression profiling microarray sequencing combined with Ingenuity Pathway Analysis (IPA) were used to explore the changes of downstream gene expression and related signaling pathways in bladder urothelial carcinoma after CHAF1A knockdown." (PMID 37575547, 2023).
glioma (2 papers, 2013 to 2021). A benign or malignant brain and spinal cord tumor that arises from glial cells (astrocytes, oligodendrocytes, ependymal cells). "Importantly, CHAF1A overexpression has been linked to tumor progression, genomic instability, and cancer susceptibility in other tumor types including glioma." (PMID 24348903, 2013).